CSF2 (colony stimulating factor 2)
Diseases named in the same sentence as CSF2 in open-access papers (continued):
Sharing a sentence is not in itself a finding about the gene and the disease.
tumor (2,665 papers, 1980 to 2026). "Together, these molecular changes alter the phenotype and functionality of mesenchymal stem cells (MSCs), indicating that the IGF2BP2/CSF2/Notch1 pathway plays a role in enhancing tumor-associated traits via epigenetic modulation of the TME." (PMID 41312360, 2025). "Consistent with their findings, we found among BCa patients, high levels of CSF2 were associated with a high T stage and tumor grade." (PMID 38817867, 2024). "In other studies, CSF2 has also been found to be closely associated with poor prognosis in some tumours." (PMID 38817867, 2024). "Expression of several other genes upregulated by ruxolitinib such as Csf2, Cx3cl1, Cx3cr1, Has1, and Ccl22 in myeloid cell populations is known to be associated with tumor progression, myeloid cell accumulation, and tumor progression." (PMID 37005447, 2023). "CSF2 upregulation was associated with increased aggressiveness of various tumor types, including head and neck cancers, glioblastomas, and bladder cancer." (PMID 36844744, 2023). "Taken together, we conclude that mutationally activated KRAS in tumor cells triggers the functional reprogramming of macrophages via a combination effect of CSF2 and lactate." (PMID 33833221, 2021). "Mutationally activated KRAS in tumor cells reprograms macrophages to a TAM-like phenotype via a combination effect of tumor-derived CSF2 and lactate." (PMID 33833221, 2021). "From the hypoxically suppressed proinflammatory genes identified by RNA sequencing, four secreted inflammatory factors (CCL20, CXCL5, CSF2 and TNFα) associated with tumor inflammation were chosen for further validation." (PMID 25978030, 2015). "Furthermore, CSF-2 produced by the neoplastic cells was able to prevent a PLX3397-mediated decrease in tumor-associated macrophages." (PMID 38791916, 2024). "Regarding the mechanism underlying increasing tumor malignancy of CSF2, studies show that maybe connect to inducing apoptosis." (PMID 38817867, 2024). "Signalling and chronic-tumour dependent hematopoietic stimulation through the release of CSF-2, CSF-3, IL-6, and other cytokines are associated with the activation of STAT3 signalling and expression of c/EBPβ transcription factor which sustain MDSC expansion and immune suppressive features." (PMID 36161514, 2023). "Moreover, CSF2 has been implicated in the regulation of tumor microenvironment formation and promotion of tumor progression through immune-dependent and immune-independent mechanisms." (PMID 37865637, 2023). "We used RT-qPCR to validate the differential expression of the five genes most strongly linked to inflammation and tumor immune responses: chemokine Ccl7, cytokine Csf2/GM-CSF, cytokine receptors Il4r and Il18r1, and inhibitor of antitumor immunity through antigen presentation Lilrb3." (PMID 36980301, 2023). "Some of these cells secrete chemokines (e.g., CCL2/MCP-1), cytokines (e.g., IL-4, IL-13) and growth factors (e.g., VEGF, CSF1/M-CSF and CSF2/GM-CSF) that trigger the recruitment of monocytes, and can promote cancer progression through the activation of tumor-associated macrophages (TAMs)." (PMID 33710603, 2021). "Interestingly, CSF-2 can induce M1-type polarization in macrophages, while CSF-2 and IL-6 derived from tumor-associated fibroblasts (CAFs) can synergistically induce the M2-type phenotype of TAMs." (PMID 33224886, 2020). "This pattern implicates CSF2 in tumor progression, potentially by fostering inflammation or modulating immune responses that favor tumor growth and metastasis." (PMID 41216204, 2025). "Across multiple preclinical tumor models, RT has been shown to increase the expression of cytokines such as IL-1β, GM-CSF (CSF2), and G-CSF (CSF3), along with chemokines including CXCL1, CXCL2, CXCL5, CCL2, and CCL5." (PMID 40805288, 2025).
tumor (continued). "We propose this work as a strategic reference for optimizing siRNA-tumor adaptive drug design, overcoming target innovation deficits (e.g., CSF2 homogeneity) and delivery limitations, thereby accelerating clinical translation of this drug class." (PMID 41041638, 2025). "In fact, CSF2 behaves as a double-edged sword in cancer by enhancing both anti- and pro-tumorigenic immune cells depending on its expression, cancer type, and tumor immune microenvironment." (PMID 40484866, 2025). "Functional analyses further suggest that CSF2 inhibits tumor cell proliferation, infiltration, and migration, indicating its potential as a therapeutic target." (PMID 41216204, 2025). "This implies that CSF2-activated neutrophils enhance tumor cell motility, potentially through remodeling of the extracellular matrix or secretion of chemotactic factors that facilitate metastasis." (PMID 41216204, 2025). "CSF2, an important cytokine, recruits a large number of immunosuppressive neutrophils and monocytes into the tumor microenvironment." (PMID 40242775, 2025). "CSF2 not only promoted differentiation and proliferation of monocytes and macrophages but also played an essential role in regulating tumor microenvironment." (PMID 40535567, 2025). "Future research should consider investigating these additional immune cells to fully understand the interplay between CSF2, neutrophils, and other immune cells, and to identify potential therapeutic targets within the tumor microenvironment." (PMID 41216204, 2025). "Recent studies have underscored the clinical relevance of CSF2 in KIRC, showing that its elevated expression is consistently associated with poor prognosis and an immunosuppressive tumor microenvironment." (PMID 41216204, 2025). "Among them, CSF2-mediated TAM reprogramming is a key regulatory node affecting tumor growth and metastasis." (PMID 41041638, 2025). "Upon binding to its ligand PD-L1, PD-1 can inhibit normal T-cell function and promote tumor growth, similar to the role of CSF2." (PMID 41216204, 2025). "In a recent study, CSF2 was shown to trigger ubiquitination and subsequent downregulation of Notch1 in MSCs, thus fostering the tumor phenotype and functionality." (PMID 41312360, 2025). "Since then, the immune function of CSF2 has been extensively studied, and its role in anti-tumor immunity is well-established in research and clinical applications." (PMID 41216204, 2025). "In AOM/DSS-induced CAC, the number of MDSCs decreased significantly in Csf2−/− mice with thwarted cancer, whereas the adoptive transfer of MDSCs from tumor-bearing mice into Csf2−/− counterparts led to cancer recurrence." (PMID 40244120, 2025). "CSF2 expression was significantly upregulated in KIRC tissues and was positively associated with advanced tumor stage and poor prognosis." (PMID 41216204, 2025). "The differentially expressed cytokines between tumor-bearing and tumor-free mice included CSF2, TGFB1, IL33, IL1B, and EGF." (PMID 41214328, 2025). "A neutrophil–tumor co-culture system was established to examine the effects of CSF2 on neutrophil polarization, tumor cell proliferation, migration, apoptosis, and autophagy." (PMID 41216204, 2025). "By screening differentially expressed cytokines in LX2 cells activated by various tumor cells, we found that the expression of CSF2, IL33, COX2, and IL17A was upregulated." (PMID 41214328, 2025). "CSF2 knockdown also inhibited tumor-induced osteoclast maturation, confirming the role of GM-CSF in osteolysis." (PMID 38342894, 2024). "Current studies have found that CSF2 is mainly secreted by macrophages, T cells, endothelial cells, fibroblasts, and tumor cells." (PMID 39036343, 2024). "Treatment of tumor stromal organoids in culture with docetaxel induces cytokine secretion (Csf3, Csf2, Il-6, Cxcl1, Cxcl2, and Tnfα) into the cell culture media while reducing levels of Vegf." (PMID 39338937, 2024).
tumor (continued). "This is achieved through the up-regulation of cytokines expressed by IL2, CCL10, and colony-stimulating factor 2 (CSF2) in tumor cells." (PMID 39100676, 2024). "The results suggest that CSF2 has a degree of accuracy in distinguishing tumor tissue and normal tissue, with AUC reaching 0.787 (CI: 0.702-0.872)." (PMID 38817867, 2024). "By leveraging information within the signatures, we discover that the HB-EGF/EGFR/MAPK axis represents a hub of tumor-stroma crosstalk, promoting the expression of CSF2 and LIF and favoring the recruitment of macrophages." (PMID 39262776, 2024). "M1 TAM plays an anti-tumor role and requires GM-CSF (CSF2) and pro-inflammatory stimuli (e.g., TNF-α) for generation." (PMID 36922564, 2023). "CSF2 was found to induce the regulation of fibrosis markers and pro-inflammatory factors in MSCs, consequently promoting tumor progression." (PMID 37865637, 2023). "It is noteworthy that CSF2 is produced by tumor cells and is regarded as a double-edged sword, as excessive or insufficient levels of CSF2 have been reported to promote tumor progression." (PMID 37566060, 2023). "In this study, we showed that CSF2 induced the ubiquitination and downregulation of Notch1 in MSCs and their subsequent pro-tumor phenotype and function, indicating a critical role of Notch1 in the reprogramming of MSCs in cancer." (PMID 37865637, 2023). "CSF2 has been shown to mediate resistance to Csf1r inhibition, and to induce accumulation of tumor-promoting myeloid cells." (PMID 37005447, 2023). "Several genes such as Csf2, Has1, Ccl22 and Tnf induced by ruxolitinib and inhibited by IKK-16 are associated with driving tumor-promoting functions in macrophages and increasing survival of tumor cells." (PMID 37005447, 2023). "CSF2 knockdown also suppressed tumor-induced osteoclast maturation, corroborating a role of GM-CSF in osteoclastogenesis." (PMID 36006737, 2022). "The Q-PCR results from all the tumors of each treatment group showed that several chemokines and cytokines were positively correlated with tumor size, including IL-4a, IL-6, IL-10, CSF-1, CSF-2, INF-r, and NOS-2." (PMID 35058524, 2022). "Activated mast cells recruit tumor-associated macrophages by CSF2, CCL3, and IL-6 secretion, resulting in increased tumor growth, as shown in a gastric cancer murine model." (PMID 34063789, 2021). "Conditioned media from lung stromal cells from obese mice promoted myeloid lineage cell migration in vitro in response to colony-stimulating factor 2 (CSF2) expression and enhanced invasion of tumor cells." (PMID 33670906, 2021). "CSF2 (GM-CSF) is known to be pro-inflammatory cytokine produced by wide variety of cells such as macrophages, T-cells, fibroblast, tumor cells, endothelial cells, and with primary production at the inflammation site." (PMID 34376762, 2021). "Its ligands are M-CSF (CSF-1), GM-CSF (CSF-2) and IL-34, and their binding to CSF-1R induces differentiation, recruitment to tumor sites, and the survival of monocytes and macrophages." (PMID 34638388, 2021). "Mechanistically, mutationally activated KRAS stabilizes HIF-1α, which drives the production of CSF2 and lactate in tumor cells." (PMID 33833221, 2021). "constructed a new type of tumor vaccine that produces both PD-1 antibody and CSF2, which has shown a promising anti-tumor effect." (PMID 34248982, 2021). "Yet in the tumor microenvironment, CSF2 is often up-regulated and suppress the immune response, resulting in a poor prognosis for patients." (PMID 33198757, 2020). "Tumour-derived CSF2 attracts, supports survival and induces pro-tumorigenic polarisation of microglia and macrophages." (PMID 32390004, 2020). "As a cytokine, CSF2 can stimulate the recruitment and maturation of dendritic cells to induce protective immunity and then exert anti-tumor effects." (PMID 33198757, 2020).
tumor (continued). "Despite CSF-1 and CSF-2 distinctively influencing macrophages, the unique properties of the tumor immune microenvironment lead tumor-infiltrating macrophages toward the protumoral phenotype." (PMID 33505964, 2020). "Accordingly, ablation of the cognate IL-33 receptor St2 limits tumor growth, and reduces mast cell-dependent production and release of the macrophage-attracting factors Csf2, Ccl3, and Il6." (PMID 31227713, 2019). "Along these lines, a vaccine that displayed mouse CSF2 on the surface of BC stem cells induces an anti-tumor immune response to metastatic BC." (PMID 27683119, 2016). "CSF2 (colony stimulating factor 2)/GM-CSF (granulate-macrophage colony stimulating factor), involved in tumor metastasis to the bone, showed a 3.34-fold increase." (PMID 19284555, 2009). "Results suggested that CSF2 may enhance tumor pro-inflammatory or pro-proliferative effects by stimulating myeloid cell proliferation and immune cell differentiation." (PMID 40535567, 2025). "Since higher T stage reflects greater tumor size and invasion, this trend supports the idea that CSF2 may contribute to tumor aggressiveness, perhaps by influencing cell proliferation or extracellular matrix remodeling." (PMID 41216204, 2025). "Moreover, CSF2 was also part of an immune-related gene signature that predicted immunotherapeutic efficacy and reflected the tumor immune microenvironment, underscoring its value in personalized therapy." (PMID 41216204, 2025). "Building on these insights, we hypothesize that CSF2 may induce N2 polarization of neutrophils through the PD-L1 pathway, thereby driving tumor progression in RCC." (PMID 41216204, 2025). "CSF2 showed significant upregulation in a variety of tumors, suggesting that the function of CSF2 in stimulating differentiation and proliferation of bone marrow-derived cells were prevalent in tumor progression." (PMID 40535567, 2025). "To evaluate the role of non–tumor-derived GM-CSF after RT, we used Csf2−/− mice." (PMID 40146036, 2025). "This differential expression suggests that CSF2 may play an active role in tumorigenesis or reflect alterations in the tumor microenvironment." (PMID 41216204, 2025). "Additionally, CSF2 upregulated PD-L1 expression in tumor cells and activated autophagy by increasing LC-3, Beclin1, and ATG7 levels." (PMID 41216204, 2025). "CSF2 is recognized for its ability to draw in and support the survival of microglia and macrophages within the glioblastoma microenvironment, thereby facilitating tumor polarization." (PMID 41312360, 2025). "Furthermore, the study lacks an in-depth exploration of the molecular mechanisms by which CSF2 modulates the tumor microenvironment, particularly its potential impact on other immune cells." (PMID 41216204, 2025). "Of note, several negative regulators of anti-tumor responses were down-regulated in CUL5 KO cells including exhaustion-associated biomarkers (NR4A2, PDCD1 and CD160), myeloid-derived suppressive cell promoting cytokine CSF2, and pro-apoptosis factor BCL2L11." (PMID 38242867, 2024). "As well, BCa with high CSF2 expression showed a high T stage and tumor grade." (PMID 38817867, 2024). "The results of the bioconfidence analysis may reflect the overall trend of high CSF2 expression in tumour tissues, whereas the experimental results reveal more directly the role of CSF2 in specific cell types and conditions." (PMID 39011666, 2024).
tumor (continued). "The chemokines CSF-1 (also known as M-CSF), CSF-2 (also known as GM-CSF), and CSF-3 (also known as G-CSF) are also shown to be expressed by PCCs, leading to decreased concentrations of anti-tumor dendritic cells and increased concentrations of immune suppressive cells within the TME." (PMID 38361931, 2024). "Aiming to determine how CSF2 affects BCa cells to inhibit tumor growth, we use flow cytometry to determine whether it could induce apoptosis." (PMID 38817867, 2024). "The plate cloning assay substantiated that diminished csf2 expression enhanced the proliferation and invasion potential of tumour cells, while the scratch assay results illuminated the facilitative role of heightened csf2 expression in tumour cell migration." (PMID 39011666, 2024). "Specifically, CSF2 may promote immune surveillance and clearance of tumours by enhancing the activity of immune cells, such as monocytes and dendritic cells." (PMID 39011666, 2024). "Consistently, we identified CSF2 could activate Nrf2 which played an important role in tumor biology." (PMID 38817867, 2024). "However, the tumor-promoting effects were attenuated upon the ablation of CSF2 in IGF2BP2 overexpression MSCs." (PMID 37865637, 2023). "However, in more advanced tumor stages, because of elevated CSF2 and IFN-γ levels in the TME, they start expressing PD-L1 and acquire an immunosuppressive phenotype, leading to worse prognoses for cancer patients." (PMID 37566060, 2023). "Additionally, cytokine granulocyte-macrophage colony stimulating factor (GM-SCF) encoding gene CSF2 and chemokine CCL5 encoding gene CCL5 were specifically expressed in TEx cells, which recruted Treg cells into tumor microenvironment and promoted tumor growth." (PMID 37550396, 2023). "Since multiple secreted factors identified above, including AREG, PAI-1, CCL2, CCL5, IL6, IL8, and CSF2, are also known to be regulated by yes associated protein (YAP), we investigated whether V2R regulates YAP in ccRCC tumor cells." (PMID 35886951, 2022). "When CSF2 was deleted in tumor cells, cell stemness could be markedly reversed through downregulating CSF2 expression." (PMID 34745015, 2021). "Our findings here also provided evidence for a tumor-supportive role of CSF2." (PMID 33833221, 2021). "However, neutralization of GM-CSF or deletion of the Csf2 gene in cancer cells had little effect on the overall MCP-1 production in tumor-bearing mice, indicating the presence of additional mechanisms that induce MCP-1 production in TMEs." (PMID 34698088, 2021). "MDSCs could induce CSCs and promote tumor immune evasion in different kinds of cancers through CSF2/p-STAT3 signaling pathway." (PMID 34745015, 2021). "In most cases, CSF2 is usually anchored to the tumor vaccine as an adjuvant." (PMID 34248982, 2021). "In addition to inducing M1 polarization, CSF2 is also responsible for the development of dendritic cells (DCs) and granulocytes, which are also APCs that exert a similar anti-tumor effect as M1 macrophages." (PMID 34248982, 2021). "Given their expression of PVR, TNFRSF14 and CD80/CD86, they might be under direct control by TIGIT+CTLA4+CSF2+TNFSF14+ tumor cells." (PMID 33968070, 2021). "Subsequently, we inquired whether KRAS is directly responsible for the production of CSF2 and lactate in tumor cells." (PMID 33833221, 2021). "As such, targeting CSF2 and/or lactate may provide a feasible route to reverse tumor-mediated immune suppression and augment the clinical effects of tumor immunotherapy." (PMID 33833221, 2021). "PD-L1/PD-1 blockade was shown to increase the anti-tumor effect of the anchored-CSF2 tumor vaccine." (PMID 34248982, 2021). "Similarly, boosting immunity by CSF-2 can be successfully replicated in some neoplastic diseases, as an immune adjuvant for promoting antitumor immunity." (PMID 33505964, 2020). "Apoptotic microglia/macrophages were detected in CSF2-depleted tumours." (PMID 32390004, 2020).